LINC01551 (long independently transcribed non-coding RNA 1551)
Synonyms: C14orf23; c14_5148
Gene: Long non-coding RNA gene on chromosome 14 (28,765,640 to 28,823,817, forward strand). Ensembl gene ENSG00000186960.
Diseases named in the same sentence as LINC01551 in open-access papers:
LINC01551 is named in the same sentence as 5 diseases in open-access papers, as found by Europe PMC text mining. Sharing a sentence is not in itself a finding about the gene and the disease. The quoted sentences say what the papers report.
glioma (2 papers, 2020 to 2024). A benign or malignant brain and spinal cord tumor that arises from glial cells (astrocytes, oligodendrocytes, ependymal cells). "In addition, the survival rate according to the expression level of LINC01551 was also significantly different in both OD and lower grade glioma patients." (PMID 32906679, 2020). "Furthermore, the comparison results of gene expression among the subtype of lower grade glioma through GEPIA, the expression amount of LINC01551 in OD, was more similar to that of normal brain tissue than to that of other subtypes." (PMID 32906679, 2020).
hepatocellular carcinoma (1 paper, 2020). A malignant tumor that arises from hepatocytes. "Although a previous report on hepatocellular carcinoma indicated that LINC01551 promotes tumorigenesis, the result of LINC01551 belonging to the ceRNA network related to hsa-miR-301a-3p was clinically positive in our study." (PMID 32906679, 2020).
LINC01551 also shares sentences with these, for which no sentence is quoted: astrocytoma (1 paper); autism (1); cancer (1).